OR5D13 (olfactory receptor family 5 subfamily D member 13)
Description:
Odorant receptor.
Tractability: Antibody: UniProt places it where antibodies can reach, with medium confidence; UniProt predicts a signal peptide or a membrane-spanning region; its Gene Ontology location is reachable by antibodies, with medium confidence. PROTAC: ubiquitination databases record sites on it.
Gene: Protein-coding gene on chromosome 11 (55,773,438 to 55,774,382, forward strand). Ensembl gene ENSG00000279761.
Subcellular location: Cell membrane
Pathways (Reactome):
Sensory Perception: Expression and translocation of olfactory receptors
Gene Ontology:
Molecular function: olfactory receptor activity; G protein-coupled receptor activity
Biological process: G protein-coupled receptor signaling pathway; sensory perception of smell; detection of chemical stimulus involved in sensory perception of smell
Cellular component: plasma membrane; membrane
Genetic constraint (gnomAD): Missense variants: 451 observed, 377.1 expected, observed/expected ratio (o/e) 1.2, 90% interval 1.11 to 1.29. Synonymous variants: 183 observed, 134.86 expected, observed/expected ratio (o/e) 1.36, 90% interval 1.2 to 1.53.
Homologues: Orthologues: dog OR5D13 (81% identical), rabbit OR5D13 (77% identical). Paralogues in human: OR5D3 (71% identical), OR5D18 (64% identical), OR5D16 (62% identical), OR5D14 (61% identical), OR5L2 (52% identical), OR5L1 (52% identical), OR5B12 (49% identical), OR5B21 (48% identical), OR8D4 (47% identical), OR5AP2 (46% identical), OR5AR1 (46% identical), OR8J1 (46% identical), and 84 more.
Diseases named in the same sentence as OR5D13 in open-access papers:
OR5D13 is named in the same sentence as 1 disease in open-access papers, as found by Europe PMC text mining. Sharing a sentence is not in itself a finding about the gene and the disease.
OR5D13 shares sentences with these, for which no sentence is quoted: pancreatic cancer (2 papers).